ENSG00000212229
Synonyms: LOC124900229
Gene: Small nucleolar RNA gene on chromosome 6 (67,210,408 to 67,210,480, reverse strand). Ensembl gene ENSG00000212229.
Gene Ontology:
Biological process: RNA processing
Cellular component: nucleolus
Homologues: Orthologues: rat LOC120099030 (77% identical). Paralogues in human: SNORD65 (82% identical), SNORD65B (79% identical), SNORD65C (77% identical).